VWA5B1 (von Willebrand factor A domain containing 5B1)
Synonyms: FLJ32784
Tractability: Antibody: UniProt places it where antibodies can reach, with high confidence; UniProt predicts a signal peptide or a membrane-spanning region; its Gene Ontology location is reachable by antibodies, with medium confidence; the Human Protein Atlas places it where antibodies can reach.
Gene: Protein-coding gene on chromosome 1 (20,290,875 to 20,359,534, forward strand). Ensembl gene ENSG00000158816.
Subcellular location: Secreted
Subcellular location (Human Protein Atlas): Mitochondria; Cytosol; Plasma membrane; Predicted to be secreted
Gene Ontology:
Cellular component: extracellular region
Genetic constraint (gnomAD): Loss-of-function variants: 113 observed, 111.98 expected, observed/expected ratio (o/e) 1.01, 90% interval 0.87 to 1.18. The upper end of that interval is the gene's LOEUF score, 1.18, which puts it in group 5 of 6, group 1 being the genes least tolerant of losing a copy. Missense variants: 1,590 observed, 1,589.5 expected, observed/expected ratio (o/e) 1, 90% interval 0.96 to 1.04. Synonymous variants: 680 observed, 652.91 expected, observed/expected ratio (o/e) 1.04, 90% interval 0.98 to 1.11.
Homologues: Orthologues: chimpanzee VWA5B1 (99% identical), macaque VWA5B1 (95% identical), dog VWA5B1 (84% identical), pig VWA5B1 (79% identical), guinea pig VWA5B1 (79% identical), rabbit VWA5B1 (79% identical), mouse Vwa5b1 (73% identical), rat Vwa5b1 (72% identical), tropical clawed frog vwa5b1 (55% identical), zebrafish vwa5b1 (6% identical). Paralogues in human: VWA5B2 (31% identical), VWA5A (19% identical), PARP4 (12% identical), ITIH4 (11% identical), ITIH3 (11% identical), ITIH5 (11% identical), ITIH6 (11% identical), ITIH1 (11% identical), VWA3B (11% identical), VWA3A (10% identical), ITIH2 (10% identical).